KDM6A (lysine demethylase 6A)
Diseases named in the same sentence as KDM6A in open-access papers (continued):
Sharing a sentence is not in itself a finding about the gene and the disease.
cancer (192 papers, 2010 to 2026). A tumor composed of atypical neoplastic, often pleomorphic cells that invade other tissues. "Mechanistically, KDM6A decreased H3K27me2/me3, which activated the expression of periostin—a protein implicated in cancer cell metastasis and EMT." (PMID 40940894, 2025). "Third, the broader applicability of this mechanism across different cancer types with varying frequencies of KDM6A mutations and phosphorylation events should be systematically evaluated." (PMID 41184251, 2025). "KDM6A was reported as a highly mutated histone demethylase in a survey of different human cancers and cancer cell lines." (PMID 41184251, 2025). "Mutations in KDM6A are frequently observed in various cancer types, particularly in primary multiple myeloma (MM) and certain types of T-cell leukemia." (PMID 39620228, 2024). "The T24 cancer cell line we used in this study has a homozygous truncating mutation at position 895 for KDM6A." (PMID 36980177, 2023). "Our findings here, which show the relationship of KDM6A with Notch signaling, provide additional insights into what goes wrong in cancer samples when KDM6A is mutated." (PMID 36980177, 2023). "Conversely, higher KDM6A expression in human cancer causes a decrease of H3K27me3 enriched heterochromatin." (PMID 35871105, 2022). "Kdm6a modulates sex differences in autoimmunity and cancer, and more recently, it has been implicated in sex differences in Alzheimer’s disease." (PMID 35871105, 2022). "The loss of KDM6A can reduce the expression of certain cancer suppressor genes, such as CDKN1A and PERP." (PMID 36052737, 2022). "KDM6A is frequently mutated in several cancer types, especially in urothelial cancer, and also in the hereditary Kabuki syndrome." (PMID 34702163, 2021). "Accordingly, all cancer cell lines used in this study exhibit these features, but they are profoundly enhanced after induction of KDM6A truncation variants." (PMID 34702163, 2021). "Although KDM6A mutations have been identified in a variety of cancers, the frequencies of the mutation are very different." (PMID 34006303, 2021). "KDM6A is mutated in several cancers, but the highest rates of mutation (20–29%) are found in UBC, with most of the genetic alterations being pathogenic nonsense, frameshift, or splice site mutations." (PMID 34768683, 2021). "In cancer, KDM6A mutations can be found throughout the whole coding region, most prevalently within the functionally relevant domains." (PMID 34702163, 2021). "Here, in seeking additional cancer driver events that can be visualized as somatic clones, we identify loss of KDM6A as possessing advantage in both intracrypt fixation and subsequent expansion." (PMID 33895166, 2021). "The epigenetic imbalance between KDM6A and EZH2 has been observed in several cancer types due to loss-of-function mutation of KDM6A or gain-of-function mutation of EZH2." (PMID 34006303, 2021). "To confirm the clonal origin of such patches, we used laser capture microdissection followed by targeted sequencing that covered 3.6 kb of exonic and flanking intronic sequence of KDM6A (24 amplicons), including sites frequently mutated in human cancers." (PMID 33895166, 2021). "In attempting to expand this methodology to X-linked genes with cancer association, clonal loss of KDM6A was identified by immunohistochemistry with 2 independent antibodies on normal human colonic epithelia." (PMID 33895166, 2021). "Somatic mutations in KDM6A are linked to various cancers, and KDM6A/UTX has a role in cell cycle regulation by mediating demethylation of retinoblastoma-binding proteins." (PMID 31924266, 2020).
cancer (continued). "This induces transcriptional changes, possibly by reduced recruitment of MLL3 and UTX/KDM6A to enhancers, and demonstrates the value of specific study of cancer mutations to discern their functional impact in cells." (PMID 32471474, 2020). "This provided further evidence that HNF1A function is not only relevant to Kdm6a‐regulated programs in the non‐tumoral pancreas, but also to Kdm6a‐deficient cancer." (PMID 32154941, 2020). "While these data point to clear mechanistic associations between KDM6A loss and cancer progression, other studies provide strong rationales for therapeutic inhibition of KDM6 proteins in cancer." (PMID 33003334, 2020). "UTX/KDM6A has been identified as a cancer driver gene via TCGA, as its loss or inactivation promotes several malignancies." (PMID 31221981, 2019). "KDM6A or UTX, located on the Xp11.2, was the first histone modifier identified as being a human cancer gene mutated and inactivated in ccRCC." (PMID 28812986, 2017). "As a result, it is likely that the KDM6A-associated phenotypes in cancer are diverse and are linked to the type and location of each driving mutation." (PMID 24622842, 2014). "Although KDM6A mutations are the most prevalent and best characterized among the KDMs, several others have been identified as significantly mutated across cancer, albeit at low frequency." (PMID 24622842, 2014). "Somatic mutations in both EZH2 and the H3K27 demethylase gene KDM6A (UTX) have been found in human cancer." (PMID 20565864, 2010). "Moreover, KDM6A is frequently mutated in various human cancer types, with most mutations being loss-of-function mutations." (PMID 40659611, 2025). "Indeed, KDM6A mutations are associated with increased “stemness” in cancer and Kdm6a KO impairs mesoderm development in vivo largely through histone demethylase-independent mechanisms." (PMID 39754175, 2025). "Thus, targeting KDM6A mutations that specifically interacting with SND1 in ESCC can be exploited as cancer cell-specific therapeutic strategies for chemotherapy." (PMID 38850159, 2024). "The identification of sensitivity to BET inhibitors in specific PDAC subtypes could lead to targeted therapy protocols, improving patient outcomes by selectively inhibiting cancer progression where KDM6A mutations are present." (PMID 38791111, 2024). "Loss or inactivation of KDM6A occurs in multiple human cancers, including MM28,29." (PMID 38355622, 2024). "Moreover, the quantity of KDM6A expression is directly associated with the abundance of NK cell infiltration in various types of cancers." (PMID 39206412, 2024). "Other alterations in this gene included missense mutations and possible deletions on chromosome X. Since KDM6A loss has been shown to sensitize cancer cells to EZH2 inhibition (for example to FDA-approved tazemetostat) and most of our patients were men, further studies would be desirable." (PMID 35664801, 2022). "KDM6A, encoding a histone demethylase, is one of the top ten mutated epigenetic cancer genes." (PMID 34702163, 2021). "On the other hand, there are plenty of KDM6A cancer somatic missense variants that are found in the database and four of the Kabuki-associated variants (C1153Y, L1200F, R1255W, and R1351Q) have been also identified from cancer patients." (PMID 33546721, 2021). "In contrast to loss of KDM6A its presence may also be associated with other cancer types such as cervical cancer, where it appeared necessary for HPVE7 expressing cells to survive and de-repress the cell cycle DNA replication inhibitor p21." (PMID 34220955, 2021). "In the TCGA study on muscle-invasive UC, about 90% of the cancers carried one or more mutations in KDM6A (encoding histone demethylase UTX), KMT2C, KMT2D (encoding histone methyltransferases MLL2 and MLL3), CREBBP, EP300 (histone acetyltransferases), and ARID1A (a SWI/SNF component)." (PMID 34885146, 2021).
cancer (continued). "In other cancers with a defective KDM6A allele on the X chromosome, the Y chromosome may be present in the cell, but may severely limit gene expression." (PMID 34768683, 2021). "Similarly, mutations (nonsense mutation, frameshift mutation, deletion, insertion etc.)in KDM6A in different cancers (renal, pancreatic, bladder, esophageal, myeloma etc.)cause the premature termination of codons and results in the loss of demethylase activity." (PMID 33003334, 2020). "Furthermore, H3K27me3 has been proposed to ‘pre-mark’ genes for de novo methylation in cancer by favoring the aberrant recruitment of DNA methyltransferases, which suggests that KDM6A mutations may play an important role for the establishment of CIMP." (PMID 25960768, 2015). "However, whether KDM6A mutation status holds significant prognostic value in cancer is yet to be determined." (PMID 24622842, 2014). "Surveying 829 polyclonal gastric microbiopsies by targeted sequencing, we find somatic 'driver' mutations in a distinctive repertoire of known cancer genes, including ARID1A, ARID1B, ARID2, CTNNB1 and KDM6A." (PMID 40108450, 2025). "Further analysis showed higher abundance of KDM6A-pSer829 in stage III/IV cancer tissues than stage I/II cancer tissues from LSCC." (PMID 41184251, 2025). "In contrast to our findings, glutamate was reduced in anoikis‐resistant cancer cells in response to KDM6A/B inhibition." (PMID 39779477, 2025). "We performed quantitative analysis of IHC sections of KDM6A-pSer829 levels in nuclei and cytoplasm of section from resected cancer and adjacent tissues." (PMID 41184251, 2025). "In contrast to the dual role of KDM6A in cancer, KDM6B has been consistently associated with cancer progression." (PMID 41085408, 2025). "Lysine demethylases 5C (KDM5C) and KDM6A were identified as cancer driver genes that support histone demethylation and hypoxia reprogramming in cancer metabolism 40-42." (PMID 39991574, 2025). "In vitro, direct glucose deprivation concentration-dependently increased KDM6A-pSer829 levels across multiple cancer cell types." (PMID 41184251, 2025). "These genes play critical roles in squamous cell differentiation and the spread of cancer, underscoring the importance of KDM6A in both developmental regulation and cancer prevention." (PMID 38791111, 2024). "UTX (KDM6A) is located on the X chromosome and carries sex-specific mutations associated with an increased cancer incidence in males." (PMID 38398123, 2024). "Escape of KDM6A from XCI in females confers protective benefits, whereas loss-of-function mutations in males are associated with an increased incidence of certain cancers." (PMID 39731171, 2024). "Similar to mutations in KDM6A, members of the type 2 lysine methyltransferase (KMT2) family (also known as MLL) are mutated in various types of cancer, suggesting that they play an important role in tumorigenesis." (PMID 38791111, 2024). "Several studies found that cancers harboring mutations in the components of the COMPASS-like complex, including KDM6A, KMT2C, and KMT2D, were associated with poor differentiation and aggressive behavior." (PMID 38791111, 2024). "GSK‐J4 is an effective dual inhibitor of H3K27me3/me2 demethylases KDM6B and KDM6A, known to promote gene silencing and cell apoptosis by inhibiting KDM6A to regulate histone methylation levels, with applications in cancer treatment." (PMID 38874525, 2024). "In cancers, nuclear KDM6A was detected in 2/6 (33.3%) of FTCs, 3/6 (50%) of PTCs, and 0/2 (0%) of PDTCs." (PMID 38610938, 2024). "Next-generation sequencing data of healthy and pathological samples, especially from cancer tissues, have indicated that UTX/KDM6A is an important gene for human diseases." (PMID 37370727, 2023).
cancer (continued). "In relation to our initial clustering analysis, most T24 KDM6A peaks were either located in the ‘IH-MULTI’ (42%) or ‘cancer’ (40%) clusters." (PMID 36980177, 2023). "UTX (encoded by KDM6A), a histone demethylase for H3K27me2/3, is frequently mutated in human cancers." (PMID 37679762, 2023). "The UTX/KDM6A histone H3K27 demethylase plays an important role in development and is frequently mutated in cancers such as urothelial cancer." (PMID 37370727, 2023). "As cell‐cycle phase transition is essential for cancer cell growth, we next investigated the changes in the cell cycle phases influenced by KDM6A deletion." (PMID 37846441, 2023). "In drug sensitivity analysis, we found that low expression of these four genes (TTN, ARID1A, KDM6A, and RB1) was positively associated with resistance to cancer therapeutics response portal (CTRP)." (PMID 37065485, 2023). "PRCC also displays mutations in previously studied cancer-related pathways; these include NF2 (Hippo pathway), SMARCB1 and PBRM1 (SWI/SNF complex), and chromatin modifier pathways (SETD2, KDM6A, and BAP1)." (PMID 38162463, 2023). "It will be important to determine in future experiments, if this relationship between KDM6A and mTORC1 is only restricted on cancer cells or is also important in normal physiology." (PMID 34509979, 2022). "To investigate the role of KDM6A/B demethylases in the transcriptional regulation of stemness genes, we treated all the detached cancer cell types with GSK J4 (a KDM6A/B) for a total period of 5 days after the initial 24 h of anoikis (detachment)." (PMID 35186918, 2022). "Loss or inactivation of KDM6A has been found to promote several malignancies, with genomic analyses revealing loss of the UTX gene coding for KDM6A in various cancers." (PMID 34572020, 2021). "Similar to the observation that KDM6A regulated ARHGDIB expression in a cancer-specific manner, among all four cell lines for different cancer types, the GSKJ4 treatment only inhibited ARHGDIB expression in HeLa and MKN-45 cells." (PMID 34006303, 2021). "While KDM6A is believed to be a tumor suppressor and is mutated in many different types of cancer, the function of KDM6B in cancer remains poorly defined." (PMID 34893606, 2021). "UTX/KDM6A encodes a major histone H3 lysine 27 (H3K27) demethylase, and is frequently mutated in various types of human cancers." (PMID 33633164, 2021). "The qPCR results showed that KDM6A did not affect the DOCK5 and DOCK8 levels in T24 cells, indicating that KDM6A regulates Rac1 activity in a cancer type-dependent manner." (PMID 34006303, 2021). "It seems therefore that KDM6A impinges on cancer pathogenesis in a highly tissue type- and context-dependent fashion." (PMID 33456567, 2021). "Concurrent action of both KDM6A and KDM6B is frequently associated with cell cycle in differentiated or cancer stem cells." (PMID 33003334, 2020). "In patient 8, two cancer gene mutations (a MAP3K1 frameshift deletion and a KDM6A frameshift insertion) were identified only in the primary tumor, suggesting both were later molecular events in the primary tumor acquired after the spread of metastatic clones." (PMID 33148332, 2020). "The disparate effects caused by LOF of either KDM6A or KDM6B indicate a complex relationship between the molecular biology of H3K27me3 removal and the cellular biology of cancer development." (PMID 33003334, 2020). "Functional experiments further support the evidence that EXITS genes can contribute to higher risk of many cancers in males, specifically for the X-linked lysine demethylase 6A (KDM6A, also known as UTX)." (PMID 33330090, 2020). "Considering the strong associations between EZH2, KDM6A, KDM6B and development, the link between these proteins and cancer cell plasticity will continue to become more apparent." (PMID 33003334, 2020).
cancer (continued). "Along the same line, the group of David Page showed that perturbing H3K27 methylation in the male germline, by knocking out the H3K27-specific demethylase KDM6a (Utx), increases cancer incidence in wild-type offspring." (PMID 32529318, 2020). "PRC2/EZH2 inhibition has emerged as a potential precision therapeutic strategy for genetically defined UTX/KDM6A null cancers that acts by rebalancing the H3K27me3 levels at specific genes." (PMID 31221981, 2019). "In sum, the cancer protective potential of KDM6A and DDX3X in normal females preferentially, is emphasised by our data, which also reinforces their particular mutation risk in male cancers." (PMID 31772231, 2019). "In other cancer types, UTX function is compromised or abolished by deleterious mutations in the KDM6A gene." (PMID 30987376, 2019). "Among the several isoforms of histone demethylases, JARID1C/KDM5C and UTX/KDM6A have been identified as cancer drivers." (PMID 31221981, 2019). "Overall, the increased expression of KDM6A suggests that it is more likely to play a role in dysregulation of H3K27me3 mediated regulation of transcription in HPV+ cancers." (PMID 29069809, 2017). "Both KDM6A and KDM6B have been implicated in a wide range of differentiation processes as well as in cancer progression, but their respective transcriptional outputs are likely to be highly context-dependent." (PMID 29029452, 2017). "In our analysis, we found that epigenetic proteins DNMT3A, HDAC2, KDM6A, and TET2 are highly mutated in variety of cancers." (PMID 26777304, 2016). "Analysis of this data shows that some epigenetic proteins such as DNMT3A, HDAC2, KDM6A, TET2 are highly mutated in most of the cancer cell lines." (PMID 26777304, 2016). "Third, mutations in chromatin regulatory factors such as SETD2, ARID1, SMARCA4, KDM6A, EP300 and MLL are emerging in various cancer types but, so far, only a few have been linked to altered methylome patterns." (PMID 25473433, 2014). "KDM6A mutations have been detected in some tumors, whereas KDM6B is upregulated in some cancers, particularly metastatic prostate carcinomas." (PMID 23673719, 2013). "A mechanistic explanation for the dramatically decreased H3K27me3 levels in HPV16 positive cervical lesions and cancers was provided by the finding that KDM6A and KDM6B are expressed at markedly higher levels in these cells." (PMID 23673719, 2013). "Considering that solid tumors exhibit glucose deficiency compared to normal tissues, we next performed immunoblotting assay to detect whether glucose deprivation increases KDM6A-pSer829 levels in cancer cells." (PMID 41184251, 2025). "Cancer cells export KDM6A from the nucleus through CDK1-triggered phosphorylation at Ser829." (PMID 41184251, 2025). "KDM6A has been reported to function as a tumor suppressor in various cancers." (PMID 41184251, 2025). "Applied to LUAD and LUSC datasets, our approach successfully identified a stable core set of pathogenic genes, including both highly expressed genes (e.g., CD74, HGF) and stably expressed genes (e.g., BRAF, KDM6A), which play critical roles in cancer progression." (PMID 40136480, 2025). "The KDM6A-pSer829 levels in 8 kinds of cancers were significantly higher than in adjacent tissues." (PMID 41184251, 2025). "KDM6A was detected in normal thyroid as well as cancer tissue samples." (PMID 38610938, 2024). "This suggests the potential involvement of KDM6A in driving cancer progression." (PMID 38791111, 2024). "Finally, gene sets enriched exclusively for upregulated genes in untreated KDM6A/KDM6B knockdown cells compared to untreated PLKO.1 cells include several related to cancer (Group 4)." (PMID 39483904, 2024).